ENSG00000269547 (novel protein)
Gene: Protein-coding gene on chromosome 19 (38,915,404 to 38,949,855, reverse strand). Ensembl gene ENSG00000269547.
Genetic constraint (gnomAD): Loss-of-function variants: 83 observed, 87.68 expected, observed/expected ratio (o/e) 0.95, 90% interval 0.79 to 1.14. Missense variants: 690 observed, 763.24 expected, observed/expected ratio (o/e) 0.9, 90% interval 0.85 to 0.96. Synonymous variants: 292 observed, 294.8 expected, observed/expected ratio (o/e) 0.99, 90% interval 0.9 to 1.09.